IL6 (interleukin 6)
Diseases named in the same sentence as IL6 in open-access papers (continued):
Sharing a sentence is not in itself a finding about the gene and the disease.
meningitis (continued). "Here, we confirmed that neonatal listeriosis also caused MG to produce high levels of TNF-a and IL-6, as reported in most neonatal human meningitis." (PMID 28335280, 2016). "The NF-κB activation in CSF cells of patients with meningitis tended to be correlated with the CSF interleukin-6 (IL-6) concentration." (PMID 26925035, 2016). "Previous works have investigated the CSF levels of inflammatory cytokines and chemokines in patients with meningitis, such as IL-6, IL-1β, TNF-α, IL-10, chemokines of the CXC family (IL-8) and growth factors using immunoenzymatic methods." (PMID 26040285, 2015). "Here, we show for the first time that during meningitis cytokine and chemokine levels also positively correlate with the bacterial burden in the brain of wild-type mice (id est IL-6, TNF-α, IL-1β, IL-10, KC, and MIP-2)." (PMID 25958220, 2015). "During the BM acute phase, an increase occurs in the expression of some cytokines, such as TNF-α and IL-6, which is useful for differential diagnosis with regard to other meningitis types such as aseptic or chronic meningitis." (PMID 26316174, 2015). "In epidemiologic study, measured IL6 of CSF is important and useful in diagnosis of meningitis.In 12 patients with viral meningitis, serum CRP level was normal." (PMID 23483792, 2012). "This study attempted to Determining HS-CRP and IL6 in serum and CSF in children suspected meningitis and Comparing value HS-CRP and IL6 in bacterial/viral meningitis." (PMID 23483792, 2012). "The data show that TNF and IL-6 are localized to the subarachnoid space in patients with meningitis although the blood–brain barrier is penetrable to serum proteins." (PMID 18475498, 1993). "Moreover, our investigations showed that A. cantonensis induces meningitis, hemorrhage, and vascular congestion in vivo and upregulates IL-1β and IL-6 secretion following ESP stimulation in astrocytes in vitro." (PMID 41284727, 2025). "Therefore, highly elevated IL-6 and IL-8 levels in our patient’s CSF support his condition of meningitis." (PMID 38678151, 2024). "To determine the cytokine expression of meningitis, we compared the CSF levels of proinflammatory cytokines IL-6, IL-17, and IFN-γ and anti-inflammatory cytokine IL-10 in patients with non-HIV and HIV-positive CM, TBM, and patients with meningitis-free syphilis." (PMID 35720334, 2022). "Overall, the analysis of cytokine concentrations indicated that CSF from meningitis patients with serotypes 6D and 23A had low levels of IL-6 whereas those with serotypes 22A, 7F and 15B/C had high levels of IL-8 and with serotype 18A had high concentrations of TNFα." (PMID 34620928, 2021). "While their approach may have been more sensitive than ours if one assumes that CSF IL-6 levels rapidly increase and decrease with the clinical course of meningitis it may have limitations with respect to patients with both, DCI and CNS infections." (PMID 33420113, 2021). "While there is promising data for TNF-α, IL-6, and IL-8 as diagnostic biomarkers in meningitis, CSF shunt infections are a biofilm rather than planktonic infection which skews the host immune response." (PMID 30626412, 2019). "During the acute phase of meningitis, increased IL-6 levels can be found in CSF of patients." (PMID 27057100, 2016). "In contrast the observed increased IL-6 trend with the IRAK4 associated rs4251552 displays the opposite picture with a stronger pro-inflammatory response, which has been shown to be harmful for meningitis outcome." (PMID 27432718, 2016). "In addition to the observed increased bacterial burden in IL-6−/− mice with meningitis, the infection with E. coli also resulted in a higher accumulation of bacteria in the liver." (PMID 27057100, 2016). "In the case of meningitis, the CSF concentration of IL-6 is increased." (PMID 27576738, 2016).
meningitis (continued). "Similarly, Parp1 gene deletion and a PARP inhibitor reduce Il1β, Il6, and Tnf expression in the brain of mice infected with S. pneumoniae, and this is correlated with reduced meningitis-induced inflammation." (PMID 25161822, 2014). "DXM decreases the expression level of IL-6, an inflammatory cytokine in the CSF, which may cause nonspecific inflammatory reactions (fever, headache, lower back pain, meningism) after MTX administration." (PMID 39859226, 2025). "Thus, the elevated level of IL-6 in the CSF is not a specific and reliable diagnostic and prognostic biomarker in the differential diagnosis of meningitis, especially in patients without sufficient signs of bacterial meningitis." (PMID 35330399, 2022). "Our previous study showed that the meningitis-associated E. coli strain PCN033 could infect astrocytes U251, induce rapid inflammatory responses, and promote the expression of many pro-inflammatory mediators such as IL-1β, IL-6, IL-8, TNF-α, MCP-1, and MIP-2." (PMID 33985523, 2021). "In order to further exclude the possibility that elevation of IL-6 levels due to bacterial meningitis might obscure the association between IL-6 levels and DCI we also studied mean IL-6 levels as potential predictors of DCI after exclusion of cases with culture-positive meningitis." (PMID 33420113, 2021). "This might be explained by multiple factors including a localized inflammatory response as elicited by bacterial meningitis, immunosuppression, downregulation of IL-6 due to additional inflammatory burden posed by meningitis, and probably due to small number of patients contracting meningitis." (PMID 29194369, 2017). "Of the 13 measured, 11 (GM-CSF, IFNγ, IL-1α, IL-1Β, IL-2, IL-4, IL-6, IL-10, IL-12, IL-18, and TNF-α) exhibited higher concentrations in the saliva of pigs with meningitis and S. suis infection." (PMID 40284818, 2025). "Through multivariate Logisitic regression analysis, it was determined that CRP, TNF-a, IL-6, PCT, and IL-1 were reliable predictors of the efficacy of Dexamethasone treatment in children with refractory purulent meningitis." (PMID 39139150, 2024). "Meanwhile, these factors were also elevatedin the control group compared to the healthygroup, which aligns with previous research and indicatesa clear elevation of that CRP, TNF-α, IL-6, PCT,and IL-1β in children with refractory purulent meningitis." (PMID 39139150, 2024). "Predictive efficacy of CRP, TNF-α, IL-6, PCT and IL-1β in children with refractory purulent meningitis treated with dexamethasone." (PMID 39139150, 2024). "During meningitis, the permeability of BBB and the expression of cytokines IL-1β, IL-6 and TNF-α increased." (PMID 36555174, 2022). "Nevertheless, neuroinflammation in meningitis can also be beneficial—the inactivation of TNF-α and IL-6 signaling in mice leads to increased lethality and neural deficits in surviving animals." (PMID 36028511, 2022). "The levels of inflammatory cytokines, including interleukin (IL)-1α, IL-1β, IL-6, and TNF-α, in brain tissues were significantly elevated after meningitis induction compared with those in normal controls." (PMID 35888118, 2022). "The expression of TNF-α, IL-6, and IL-1β in the APEC XM group was in line with that previously reported in in vivo or in vitro E. coli meningitis studies." (PMID 34529552, 2021). "In the hippocampus, we observed increased levels of pro-inflammatory cytokines, such as IL1-α, IL1-β, IL-6, IL-18, TNF-α, and INF-γ (P < 0.05) in the 24-h meningitis group." (PMID 31901235, 2020). "The results from this study demonstrate a storm of inflammatory cytokines, such as IL1-α, IL-1β, IL-6, IL-18, TNF-α, and INF-γ, in the 24-h meningitis group." (PMID 31901235, 2020). "As expected, in the PFC, we observed increased levels of pro-inflammatory cytokines such as IL1-α, IL1-β, IL-6, IL-17, TNF-α, and INF-γ (P < 0.05) and decreased levels of IL-7, IL-10, and IL-13 (P < 0.05) in the 24-h meningitis group." (PMID 31901235, 2020).
meningitis (continued). "In early meningeal infection, the pro-inflammatory cytokines interleukin (IL)-8, IL-1, tumor necrosis factor alpha (TNF-α), and IL-6 have been shown to be elevated." (PMID 30626412, 2019). "It is well established that inflammatory cytokines can contribute to BBB dysfunction in human disease, including studies of the BCSFB using albumin ratios in meningitis showing relationship to TNF- α, and cardiac surgery showing relationship to IL-6 and IL-8." (PMID 30186149, 2018). "IL-6, IL-8, and TNF in CSF have in several studies been found to be elevated in meningitis and have even been proposed as biomarkers in CSF for bacterial meningitis." (PMID 30470234, 2018). "The goal of the current study was to examine the interaction between IL-6 and TNFR1 as receptor for TNF-α and the innate immune response in vivo in a model of Streptococcus pneumoniae-induced meningitis." (PMID 27057100, 2016). "IL-6 contributes directly to blood brain barrier (BBB) permeability and boosts intracranial pressure and cerebral oedema in meningitis." (PMID 26040285, 2015). "Notably, in experimental meningitis, PARP1-deficient mice and mice treated with the PARP inhibitor, 3 aminobenzamide (3-AB), display reduced leukocyte infiltration and meningeal inflammation, and this is correlated with impaired expression of Il1β, Il6 and Nos2." (PMID 25161822, 2014). "The measurement of IL6 and HS-CRP in serum and CSFof children suspected meningitis and compared bacterial and viral meningitis." (PMID 23483792, 2012). "When a panel of cytokines (including GM-CSF, IFNγ, IL-1α, IL-1β, IL-1ra, IL-2, IL-4, IL-6, IL-8, IL-10, IL-12, IL-18, and TNF-α) was measured in saliva from healthy pigs and in pigs with meningitis and S. suis infection, upregulation of several cytokines was observed in the diseased animals." (PMID 40284818, 2025). "We thus confirm previous studies showing enhanced IFN-γ production by PBMC from meningitis patients and show that the HSV-2-induced production of several other cytokines, i.e. IL-6, LIF and IL-8, are produced to a higher degree in PBMC from meningitis patients." (PMID 40534882, 2025). "Therefore, CRP,TNF-α, IL-6, PCT, and IL-1β can be applied as one ofthe crucial indicators to evaluate the curative effect ofrefractory purulent meningitis in children." (PMID 39139150, 2024). "Notably, CRP andIL-1β demonstrated superior predictive performance,suggesting that CRP, TNF-α, IL-6, PCT, and IL-1β canserve as effective indicators for evaluating efficacy ofdexamethasone treatment in children with refractorypurulent meningitis." (PMID 39139150, 2024). "This has been shown to be the case in other contexts such as meningitis, where it was found that blood IL-6 was not as specific a marker as IL-6 in the cerebrospinal fluid." (PMID 37486461, 2023). "Of note, Lenski and co-workers used CSF IL-6 levels at the time of first diagnosis of DCI or meningitis rather than peak values over several days." (PMID 33420113, 2021). "In meningitis pathophysiology, BBB disruption is an obligatory outcome, accompanied by acute inflammatory responses, with the release of multiple inflammatory factors such as TNF-α, IL-1β, IL-6, IL-17A, MCP1, and GRO-α." (PMID 31783671, 2019). "Contrary, in CSF of patients with meningitis caused by N. meningitidis, no tendency was observed for a positive correlation between BPI and either TNFα or IL-6 levels." (PMID 30581431, 2018). "Levels of IL-6 seem to be increased in meningitis regardless of the presence and type of infection (bacteria or virus), making this cytokine an ideal biomarker for meningoencephalitis prognosis." (PMID 26286516, 2015). "High levels of the pro-inflammatory cytokines such as interleukin 1 beta (IL-1 beta), interleukin 6 (IL-6) and tumor necrosis factor alpha (TNF alpha), were detected in the cerebro-spinal fluid (CSF) of patients with meningitis, which is typical of the severe inflammation of the brain." (PMID 23874613, 2013).
meningitis (continued). "In Jamil report, IL-la had the highest sensitivity and negative predictive value in meningitis and, IL-6 had the highest specificity and positive predictive value." (PMID 23483792, 2012). "Proinflammatory cytokines (IL-1β, IL-6, TNFα, MCP-1, MIP-1alpha, and RANTES) and adhesion molecules (CD44 and ICAM-1) were significantly reduced in the cerebrospinal fluids of the α7-/- mice with E. coli meningitis." (PMID 21966399, 2011). "In patients with meningitis, median levels of TNF in 31 paired samples of cerebrospinal fluid (CSF) and serum were respectively 783 pg/ml and below detection limit (p < 0.001) and median levels of IL-6 were 150 ng/ml and 0.3 ng/ml (p < 0.0001)." (PMID 18475498, 1993). "The results of our retrospective study demonstrated that IL-6 is a non-specific biomarker and its elevated concentrations in patients with signs of post-neurosurgical meningitis could be due to both meningitis and main disease." (PMID 35330399, 2022). "Patients with signs of post-neurosurgical meningitis (n = 30) had lower median values of glucose and higher values of cell count, neutrophils, lactate, protein, 3-(4-hydroxyphenyl)lactic acid (p-HPhLA), and interleukin-6 (IL-6) than patients without signs of post-neurosurgical meningitis (n = 52)." (PMID 35330399, 2022). "The serum proinflammatory cytokines in STSS patients, especially interleukin 6 (IL-6), IL-1β, and tumor necrosis factor (TNF), gamma interferon (IFN-ɣ), IL-12, and monocyte chemoattractant protein 1 (MCP-1), are significantly higher than those in meningitis patients." (PMID 32922370, 2020). "Our data as well as multiple studies in pediatric meningitis demonstrate that TNF-α, IL-6, and IL-8 are present in the CSF of patients with neurologic infection; however, these are likely not good markers for differentiating shunt infection from meningitis." (PMID 30626412, 2019). "Serum IL-6 levels were unchanged in patients with meningitis as compared to aSAH patients without infections except on day 3 as shown by multivariate analysis revealing a negative independent association between serum IL-6 and meningitis (OR = 0.002, p = 0.024, 95% CI = 0.0–0.4)." (PMID 29194369, 2017). "However, such a correlation is not observed for IL-6, IL-10, and KC in C/EBPδ−/− mice, which suggests that C/EBPδ directly drives transcriptional activity of these inflammatory mediators during meningitis." (PMID 25958220, 2015). "Thus, the main diagnosis could be the reason for the elevated levels of IL-6 but not for post-neurosurgical meningitis." (PMID 35330399, 2022). "We also found that AnxA1 decreased neutrophil adhesion through Fpr2, and AnxA1 decreased IL-6 expression through the Fpr2/p38/COX-2 pathway, which may clarify the mechanism by which the protein decreased cytokine expression and brain damage during S. suis meningitis." (PMID 33318141, 2021). "The IFN-γ and LIF (but not IL-6 and IL-8) responses to HSV-2 antigen were also higher in PBMC from meningitis patients, indicating that these two cytokines represented recall responses." (PMID 40534882, 2025). "In our study, we evaluated the concentrations of different biomarkers (IL-6, NSE, S100, and 5HIAA) and some aromatic metabolites, including those of microbial origin, in patients with and without signs of post-neurosurgical meningitis." (PMID 35330399, 2022). "In CSF, IL‐6, IL‐10, and IFN‐γ showed rapidly increase in EVM group while cytokines sharply declined in control group without meningeal infection." (PMID 31912935, 2020). "The concentrations of the cytokines IFN-γ, IL-6 and TNF and the chemokine CCL2 were not significantly different between the WT and GKO meningitis animals, but a significantly lower concentration of IL-1β in the CSF was observed in the GKOs (p = 0.005)." (PMID 31700009, 2019).
meningitis (continued). "Microglia of P4 neonates born to NV and LMWT-infected mothers presented high levels of IL-6, IL-10 and TNF-α and lacked production of IL-12p40; a Th2 pattern similar to the cytokine profile reported in meningitis and encephalitic cases of listeriosis." (PMID 28903312, 2017). "In patients with septic shock without meningitis, median levels in paired samples of CSF and serum were respectively below detection limit and 65 pg/ml (not significant, (ns)) (TNF, eleven patients) and 1.3 ng/ml–3 ng/ml (ns) (IL-6, nine patients)." (PMID 18475498, 1993). "Eighteen hours after the initiation of meningitis, the level of TNF-α was significantly inhibited by CPZ (the cytokine that was initially shown to be more strongly dependent on endocytosis), but the level of IL-6 was not, although IL-6 levels showed a decreasing trend." (PMID 36028511, 2022).